MCL1 (MCL1 apoptosis regulator, BCL2 family member)
Diseases named in the same sentence as MCL1 in open-access papers (continued):
Sharing a sentence is not in itself a finding about the gene and the disease.
tumor (continued). "Across different freshly resected IDHwt GBM samples, we found that targeting both MCL-1 and BCL-xL led to an extensive induction of apoptosis and sustained reduction in tumour cell viability ex vivo, without compromising tissue and vessel integrity." (PMID 35473984, 2022). "Neither MCL1 nor BCLW mRNA showed any correlation with clinical parameters, but BCLW showed higher expression in large tumours." (PMID 34903710, 2021). "Despite the increase in phospho-SRC signal in DEXA treated tumours, we did not detect a significant increase in BCL2L1 and MCL1 expression." (PMID 33478100, 2021). "They demonstrated that siRNA-mediated suppression of MCL-1 enhanced the killing of these lines by their cognate targeted therapies more robustly than other BCL-2 family members, independent of tumor lineage, driver oncogene, or targeted therapy." (PMID 31988312, 2020). "Our dosing was at least 5–10 times less than the reported studies that combine a MCL1 inhibitor with ABT-199, and our approach showed significant tumor shrinkage with no obvious toxicity." (PMID 32513939, 2020). "Tumors were histopathologically identical to those developed in c-Myc/MCL1 mice, implying that the absence of FASN does not modify the tumor phenotype in this mouse model." (PMID 33187130, 2020). "Moreover, we could also observe a significant increase in ∆% priming after incubating tumor cells with targeted agents, such as S63845, ABT-199, and SP2509 and we also identified possible anti-apoptotic adaptations to those treatments by BCL-xL and MCL-1 that we will further explore." (PMID 32801295, 2020). "Despite high expression in tumor compared to normal tissues, expression levels of BCL-XL and MCL-1 did not correlate with patient outcome in SCCHN." (PMID 31801952, 2019). "Pertinently, the sensitivity of some tumor cell lines to BH3 mimetic ABT737, which targets BCL-2, BCL-XL, and BCL-W but not MCL-1, is enhanced by 2-deoxyglucose (2DG)." (PMID 30538285, 2019). "However, A-1210477 although highly specific for MCL-1, its ability to bind to serum proteins may limit its bioavailability and this could lead to drug resistance in preclinical models and patients as sufficient amount may not reach the tumour site." (PMID 29580266, 2018). "Most tumor samples with high MCL-1 levels also expressed BCL-xL, while neither MCL-1 nor BCL-xL was detected in one-third of the 18 samples." (PMID 30250075, 2018). "Interestingly, a significant increase in BCL-2/MCL-1 was displayed by HCC samples, that was not presented by the neighboring cirrhotic tissue, suggesting that this modification could be associated to tumor development." (PMID 29682179, 2018). "This suggests that a tumor’s lack of expression of BH3 pro-apoptotic proteins would not prevent them from responding to the combination of ABT-263 and MCL-1 inhibitors." (PMID 30185782, 2018). "Given the range of responses, we show that CIVO, a multiplexed tumor micro-dosing technology, represents a viable functional precision medicine approach for differentiating responders from non-responders to BCL-2/MCL-1 targeted therapy." (PMID 29269870, 2017). "Affymetrix mRNA profiling of the in vivo tumor samples revealed no significant changes in BCL-2, MCL-1, BCL-XL and BIM mRNA levels after ABT199 treatment." (PMID 27056887, 2016). "However, the levels of anti-apoptotic machinery members (BCL-2, BCL-XL and MCL-1) were not dramatically affected indicating the strong tumor cell inhibition and induction of apoptosis in EC cells by ABT263 may be due to other mechanisms in addition to its canonical anti-BCL2 family." (PMID 26317542, 2015). "For instance, expression profiling of bulk tumor would have revealed high expression of c-Myc, L-Myc, Mcl-1, Bcl-x, c-Flip, and TRAIL, but (critically) would not have revealed which isoforms of Mcl-1, Bcl-x, c-Flip, and TRAIL were being expressed." (PMID 23527012, 2013). "Conversely, MCL1 and BID expression were lower in tumor cells compared to non-tumor cells." (PMID 39122703, 2024).
tumor (continued). "Indeed, multiple studies assessing administration of these inhibitors, including on the same day, reported that specifically inhibiting MCL-1 and BCL-2 was effective at reducing tumor burden, without overt toxicity concerns." (PMID 37864894, 2023). "Our TCGA analysis suggests that increases in both the expression of B3GNT2 as well as copy number of MCL1 and B3GNT2 may generally promote tumor initiation or progression in the absence of immunotherapy." (PMID 35338135, 2022). "Together, these results suggest that increased expression of MCL1 and B3GNT2 may promote tumor progression and immune evasion in patients, whereas JUNB is not as clinically relevant across diverse tumor types." (PMID 35338135, 2022). "Interestingly, dinaciclib did not reduce expression of MCL-1 in SKOV-3 cells as has been previously demonstrated in OC cell line, A2780, and in other tumor types." (PMID 36505806, 2022). "The Western blotting showed a down‐regulated expression of MARCH1, PI3K, P‐AKT, β‐catenin, Bcl‐2 and Mcl‐1 and an up‐regulated expression of pro‐apoptosis‐related Cleaved caspase‐3 and Cleaved caspase‐7 in the HCC tumours injected with MARCH1 siRNA compared with the negative controls." (PMID 30793486, 2019). "Although BCL-XL and MCL-1 were not prognostic indicators in SCCHN, dual inhibition resulted in extensive apoptosis in all preclinical models including tumor explants, as well as a decreased tumor burden in zebrafish xenografts." (PMID 31801952, 2019). "Since down-regulation of Mcl-1 has this strong effect, A1 seems to play no role in resistance to ABT-737 and it has been said that A1 is not expressed in most tumours although this may be a problem of sensitivity of A1 protein detection." (PMID 20576107, 2010). "Inhibition of MCL1 led to replication stress, DNA damage, and reduced proliferation, even in cells resistant to apoptosis—suggesting that MCL1-targeting BH3 mimetics may also limit tumor growth via non-apoptotic mechanisms." (PMID 41155156, 2025). "Thus, when chemotherapy was combined with THZ1 at a dosage that did not affect proliferation, MCL1 was also considerably reduced, indicating that THZ1 may combine effectively with chemotherapy to induce tumor cell death synergistically." (PMID 35945614, 2022). "Unexpectedly, MCL-1 levels were also observed to be lower in tumours treated with BH3-mimetics, though this could be a consequence of apoptosis induction in the cells due to Caspase-3 activation, though it was not apparent in tumours treated with Cisplatin alone." (PMID 33298868, 2020). "Mcl-1, being an anti-apoptotic protein, may be more likely to be an important mediator and participant in the signal pathways involved in the anti-apoptotic effects of OPN in GIST, rather than the different mechanisms regarding tumor proliferation and progression." (PMID 24947165, 2014).
infection (89 papers, 2006 to 2026). The state of being infected such as from the introduction of a foreign agent such as serum, vaccine, antigenic substance or organism. "This study identifies CT181 as a previously undescribed secreted effector that associates with the host pro-survival protein Mcl-1 and is linked to prolonged neutrophil survival during infection." (PMID 42138418, 2026). "When comparing the titers of the infected transduced cells, human MCL1 (huMCL1) caused a 4-log decrease in viral titers compared with the GFP cells at 6 h post-infection." (PMID 40464580, 2025). "Of specific note was the rapid loss of MCL-1, coinciding with activation of apoptosis at 15 hours post infection." (PMID 39226332, 2024). "Our findings are in support of other findings which have shown loss of MCL-1 as a driver of intrinsic apoptosis during infection, but are the first observations that MNV infection results in a dramatic reduction of this protein." (PMID 39226332, 2024). "Although the anti-apoptotic Bcl-2-family protein Mcl-1 was strongly upregulated upon infection, Mcl-1-deficient cells and cells where Mcl-1 was pharmacologically inactivated were still protected." (PMID 35397654, 2022). "Specifically, MAP infection in macrophages induced Notch-1 and IL-6 signaling and resulted in the hijacking of MCL-1 causing apoptosis and persistence infection." (PMID 33072191, 2020). "This induction of PPAR activity drives the expression of the pro-survival protein MCL-1, as shown by the gene expression analysis during infection and the loss of MCL-1 expression during infection in a PPAR knockout model." (PMID 32508813, 2020). "Suppression of MCL1 expression was consistent with the degree of susceptibility to each virus at 2 days post infection." (PMID 30261081, 2018). "Infection of Mcl-1-deficient MEFs with VACV provided substantial protection against ABT-737, while MCMV-infected cells were completely protected." (PMID 27537523, 2016). "Infection of HeLa human epithelial cells with MVA or MVAΔF1L caused the loss of anti-apoptotic Mcl-1 after about 8–16 h post infection." (PMID 27537523, 2016). "Infection with VACV induced the loss of Mcl-1 in macrophages, as we had observed during infection with MVA." (PMID 27537523, 2016). "Infection can also cause the upregulation of host anti-apoptotic factors such as MCL1 and IAP complexes." (PMID 26779446, 2015). "Thus, the wild-type AdV infection causes a decrease in MCL-1 but also counteracts the consequences of its deficiency." (PMID 38256213, 2024). "In this work, we have described the role of MCL-1 in infections caused by various viruses." (PMID 38256213, 2024). "In our study, we found an infection time of 24 h, and the cytokine profile suggests a pro-inflammatory microenvironment; the MCL-1 level probably requires a more prolonged time of infection to be modulated and could be associated with the M2 phenotype." (PMID 35631013, 2022). "The side effects of a STAT5 and MCL1 inhibitor combination therapy may be comparable to the side effects of the conventional standard induction therapy, including elevated risk of infection and increased bruising or bleeding." (PMID 34360855, 2021). "Therefore, the loss of Mcl-1 interaction with the chlamydial inclusion and functional effect due to higher ubiquination levels is likely maintained during mammalian infection by the Tn-cdu1 mutant strain." (PMID 28347402, 2017). "MVA infection however protected Mcl-1-deficient cells against ABT-737." (PMID 27537523, 2016). "Multiple studies also only analyze the detection of apoptosis after 24 h post-infection, whereas we see the antiviral activity of MCL1 as early as 6 h post-infection." (PMID 40464580, 2025). "Western blotting at 3 h post-infection revealed that both the W83 and the gingipain-null mutant (ΔKRAB) induced expression of three anti-apoptotic proteins, A1, Mcl-1, and Bcl-xL, by murine HoxB8 neutrophils." (PMID 39936030, 2025).
infection (continued). "The concurrent upregulation of an anti-apoptotic factor (MCL1) with only a mild rise in a pro-apoptotic caspase suggests that RSV tilts the balance toward cell survival in the early phase of infection." (PMID 40630640, 2025). "TRP120-mediated degradation leads to upregulation of oncoproteins (c-MYC, NICD,c-Jun and MCL1) during infection." (PMID 40028182, 2025). "Intriguingly, MCL-1 was also found to colocalize with E. chaffeensis morulae throughout infection, suggesting the possibility of a distinct, post-translational regulatory mechanism like that observed in Chlamydia trachomatis." (PMID 41115066, 2025). "Collectively, these results demonstrate that E. chaffeensis modulates expression of STAT target genes, including MCL-1, during infection." (PMID 41115066, 2025). "Myeloid Cell Leukemia-1 (Mcl-1) is an anti-apoptotic BCL-2 family protein that is notably upregulated in RSV infection after initial infection." (PMID 40951311, 2025). "Validation of this screen by overexpression of MCL1 in porcine cells proved that it does indeed inhibit FMDV viral replication as early as 6 h post-infection." (PMID 40464580, 2025). "T4SS+Legionella-infected DCs had significantly decreased Mcl-1 levels by 4 h post-infection compared to uninfected cells." (PMID 40530878, 2025). "In T4SS+Legionella-infected DCs, cleavage of caspases-8, -9, -3, and -7 began at 4 h post-infection, coinciding with the decrease in Mcl-1 levels." (PMID 40530878, 2025). "To understand how Chlamydia extends neutrophil lifespan, we examined Mcl-1 expression during infection." (PMID 41051248, 2025). "Given our prior research establishing MCL-1 upregulation at the protein level during infection, we assessed the relevance of STAT3 in MCL-1 upregulation and apoptotic inhibition." (PMID 41115066, 2025). "The repression of translation, loss of MCL-1 and cleavage of PARP in only the NS3 transfected samples leads us to propose that NS3 is responsible for inducing apoptosis in response to infection." (PMID 39226332, 2024). "It has been shown that infection with some viruses results in either stabilisation or depletion of MCL-1 to regulate apoptosis." (PMID 39226332, 2024). "The change in the MCL-1 level plays an important role in pathogen replication and dissemination, impairs the host immune response, and contributes to the persistence of infection." (PMID 38256213, 2024). "For SARS-CoV-2 it was shown that expression of the N protein binds MCL-1 to prevent apoptosis and promote virus replication, whereas infection with VSV results in depletion of MCL-1, subsequent induction of cell death programs and restricts virus replication." (PMID 39226332, 2024). "Our previous observations with siRNA silencing of PPARγ showed a decrease in M. tb-induced MCL-1 gene expression beginning at 6h post-infection." (PMID 37000865, 2023). "At the later phase of infection, the level of HIF-1α decreases sharply, suggesting that Chlamydia employs other mechanisms to preserve the expression of MCL-1 during infection." (PMID 37374883, 2023). "Altogether, these data reveal that CREB signaling is important for M. tb-induced gene and protein expression of COX2 and MCL-1 early post-infection in human macrophages, as well as PGE2 production." (PMID 37000865, 2023). "In the current study, we found that M. tb infection begins to induce MCL-1 gene expression at 1h post-infection and protein expression as early as 3h post-infection." (PMID 37000865, 2023). "Ctr-infection blocked apoptosis induced by co-inhibition of Mcl-1 and Bcl-XL (HCT116 cells show little sensitivity to ABT-737)." (PMID 35397654, 2022). "Significant upregulation of MCL-1 during infection by L. donovani was also reported by another group, which further suggests infection-induced MCL-1 to be localised in the host mitochondria." (PMID 35531875, 2022).
infection (continued). "While the data strongly support the role of Notch-1 in the modulation of macrophage response during infection, it also suggests that MCL-1 is involved and should be elucidated further." (PMID 32635645, 2020). "Most importantly, blocking Notch signaling with DAPT reduced MAP infection and the inflammatory response which strongly indicates that Notch signaling is essential for IL-6 and MCL-1 expression in response to intracellular infections such as MAP or M. bovis." (PMID 32635645, 2020). "The expression of MCL-1, when a phagocyte is attempting to control an intracellular infection, significantly impairs the host’s ability to restrict infection." (PMID 32508813, 2020). "Small interfering RNA targeting Mcl1 exhibit increased cell death of HCMV-infected monocytes in comparison to mock infection and use of control siRNA." (PMID 32765441, 2020). "It is important to note that MCL1 expression is tight controlled during the infection cycle of M. anisopliae, with the higher expression occurring during hemolymph colonization." (PMID 31711419, 2019). "Infection of peripheral blood monocytes with HCMV leads to induction of anti-apoptotic proteins, such as myeloid cell leukemia-1 (Mcl-1) and B cell lymphoma-1 (Bcl-1), as causes delay of apoptosis in the infected cells." (PMID 31491031, 2019). "To confirm the BCLXL-dependent survival of cells upon infection with flaviviruses, we generated Huh7 cell lines that were deficient in either BCLXL or MCL1 (BCLXKO or MCL1KO)." (PMID 30261081, 2018). "Similar to gene expression, Mcl-1 protein was induced as early as 6 h after infection with M. tb, and was maintained for at least 72 h." (PMID 29928066, 2018). "Under normal conditions, Mcl-1 associates with the proapoptotic BAK protein to maintain BAK in an inactive state whereas downregulation of Mcl-1 proteins is triggered by DNA damage, such as infection by viruses." (PMID 30176860, 2018). "Our lab demonstrated that the first step in the HCMV-mediated inhibition of monocyte apoptosis occurs within the first 48 h post infection (hpi) and depends upon the up-regulation and stabilization of Mcl-1." (PMID 30274264, 2018). "We found that M. tb significantly increased Mcl-1 gene expression in MDMs as early as 6 h post infection, and that this was maintained through at least 48 h." (PMID 29928066, 2018). "Expression of MCL1 was reduced in the highly susceptible cell lines upon infection with JEV; in contrast, MCL1 was stably expressed in cell lines with low susceptibility." (PMID 30261081, 2018). "Viral regulation of Mcl-1 and Bcl-2 expression allows for strict control over caspase function during infection, allowing the virus to not only control cell survival, but also direct monocyte-to-macrophage differentiation." (PMID 30274264, 2018). "In this study, we showed that infection with flaviviruses reduces expression of MCL1 but remaining BCLXL delayed apoptosis in infected cells." (PMID 30261081, 2018). "No MCL1 protein was detected in the insoluble fraction of cell lysates, suggesting that the total amount of MCL1 protein is decreased by the infection with flaviviruses." (PMID 30261081, 2018). "Our data support this model in that early infection of B cells by EBV promotes MCL-1 as a critical apoptotic regulator similar that observed for GC B cells in the mouse." (PMID 28425914, 2017). "Maintenance of increased Mcl-1 levels in the mid and late phases of infection, however, required in addition stabilization of the protein." (PMID 28347402, 2017). "Early in infection, expression of Mcl-1 is increased by the activation of the RAF/MEK/ERK and the MAPK/AKT signaling pathway." (PMID 28347402, 2017). "When cells were transfected with a miR-26a mimic along with a plasmid expressing KLF4 prior to infection, the levels of Mcl-1 increased compared to cells transfected with miR-26a mimic alone." (PMID 28558034, 2017).